TBC1D8 (TBC1 domain family member 8)
Description:
May act as a GTPase-activating protein for Rab family protein(s).
Synonyms: VRP; HBLP1; AD3; GRAMD8; TBC1D8A
Tractability: Antibody: the Human Protein Atlas places it where antibodies can reach. PROTAC: ubiquitination databases record sites on it; its protein half-life has been measured.
Gene: Protein-coding gene on chromosome 2 (101,005,934 to 101,252,866, reverse strand). Ensembl gene ENSG00000204634.
Subcellular location (Human Protein Atlas): Nucleoplasm; Plasma membrane; Centrosome
Gene Ontology:
Molecular function: protein binding; GTPase activator activity
Biological process: regulation of cilium assembly; blood circulation; positive regulation of cell population proliferation; system process
Cellular component: membrane
Genetic constraint (gnomAD): Loss-of-function variants: 63 observed, 112.82 expected, observed/expected ratio (o/e) 0.56, 90% interval 0.46 to 0.69. The upper end of that interval is the gene's LOEUF score, 0.69, which puts it in group 2 of 6, group 1 being the genes least tolerant of losing a copy. Missense variants: 1,259 observed, 1,392.8 expected, observed/expected ratio (o/e) 0.9, 90% interval 0.86 to 0.95. Synonymous variants: 531 observed, 567.56 expected, observed/expected ratio (o/e) 0.94, 90% interval 0.87 to 1.
Homologues: Orthologues: chimpanzee TBC1D8 (99% identical), dog TBC1D8 (94% identical), macaque TBC1D8 (94% identical), rat Tbc1d8 (92% identical), mouse Tbc1d8 (90% identical), rabbit TBC1D8 (87% identical), pig TBC1D8 (84% identical), guinea pig TBC1D8 (83% identical), tropical clawed frog tbc1d8b (74% identical), zebrafish TBC1D8 (48% identical). Paralogues in human: TBC1D8B (52% identical), TBC1D9 (50% identical), TBC1D9B (50% identical), SGSM3 (15% identical), RABGAP1 (13% identical), RABGAP1L (12% identical), TBC1D2B (12% identical), TBC1D2 (11% identical), TBC1D1 (11% identical), TBCK (11% identical), EVI5L (11% identical), TBC1D4 (11% identical), and 33 more.
Diseases named in the same sentence as TBC1D8 in open-access papers:
TBC1D8 is named in the same sentence as 20 diseases in open-access papers, as found by Europe PMC text mining. Sharing a sentence is not in itself a finding about the gene and the disease. The quoted sentences say what the papers report.
ovarian carcinoma (6 papers, 2020 to 2024). A malignant neoplasm originating from the surface ovarian epithelium. "TBC1D8 is unregulated in the aggressive ovarian cancer cells and it is associated with poor prognosis in these patients." (PMID 34751020, 2022). "TBC1D8 interacts with PKM2 via its Rab-GAP TBC domain to promote aerobic glycolysis in ovarian cancer." (PMID 38766486, 2024). "The function of TBC1D8 has been studied in ovarian cancer, where it was found to be significantly upregulated." (PMID 38766486, 2024). "It has been shown that TBC1D8 is significantly up-regulated in invasive ovarian cancer cells, which drives the occurrence and metabolic reprogramming of ovarian cancer." (PMID 35918393, 2022). "While it has been reported that TBC1D8 can regulated metabolic reprogramming to drive ovarian cancer progression, little research has been reported on TBC1D17 in cancer." (PMID 35918393, 2022). "By binding to PKM2, TBC1D8 hinders PKM2 tetramerization to decrease pyruvate kinase activity and promote aerobic glycolysis, leading to ovarian cancer tumorigenesis and metabolic reprogramming." (PMID 38766486, 2024). "TBC1D8, an activated factor of the GTP enzyme, involved in DM, participates in ovarian cancer tumorigenesis and metabolic reprogramming." (PMID 34751020, 2022). "Although research on TBC1D8 in HCC is lacking, it has been found to be an independent prognosis marker in ovarian cancer." (PMID 32931665, 2020).
osteoporosis (3 papers, 2010 to 2020). A condition of reduced bone mass, with decreased cortical thickness and a decrease in the number and size of the trabeculae of cancellous bone (but normal chemical composition), resulting in increased fracture incidence. "A genome wide analysis found that the TBC1D8 gene is closely associated with osteoporosis." (PMID 33315972, 2020). "We found that the methylation level of the promoter region CpG islands in the TBC1D8 gene was significantly lower in those with osteoporosis compared to controls." (PMID 33315972, 2020). "The TBC1D8 gene has been recently discovered to have a correlation with osteoporosis." (PMID 33315972, 2020). "Finally, we also observed that TBC1D8 is negatively correlated with high density lipoprotein in postmenopausal women with osteoporosis." (PMID 33315972, 2020). "Furthermore, we investigated whether an association exists between the CpG island methylation levels in the promoter region of the TBC1D8 gene and osteoporosis incidence." (PMID 33315972, 2020). "With elevated methylation levels of TBC1D8, the GTP enzyme was activated to enhance osteoclast activity, resulting in osteoporosis." (PMID 33315972, 2020).
atherosclerosis (2 papers, 2019 to 2021). A disease characterized by the build-up of fatty material and calcium deposition in the arterial wall resulting in partial or complete occlusion of the arterial lumen. "Another GWIS on gene-smoking interactions identified two novel genetic variants (e.g., rs1192824 and rs77461169) in the regulatory region of TBC1 domain family member 8 (TBC1D8) gene that affect carotid intima-media thickness and thus, increased consequent risk for atherosclerosis." (PMID 34445123, 2021). "Our study is therefore confirming the importance of TBC1D8 gene-environment interaction in atherosclerosis pathophysiology." (PMID 32117412, 2019).
Obesity (2 papers, 2017 to 2021). Accumulation of substantial excess body fat. "One study noted that DNAm of TBC1D8 was associated with obesity, while others showed that expression of TBC1D8 was positively associated with obesity in abdominal and gluteal subcutaneous adipose tissue." (PMID 34301314, 2021). "For example, the interleukin-6 receptor (IL-6R) is linked to increased risk of asthma and obesity, and its expression is positively associated with expression of TBC1D8 and negatively with expression of TBC1D16." (PMID 34301314, 2021). "Three of the four identified genes, TBC1D16, TBC1D8, and RASA2, have been previously implicated in relation to asthma and/or obesity/BMI, supporting the informativity of genes identified in this study." (PMID 34301314, 2021).
acute lymphocytic leukemia (1 paper, 2019). "TBC1D8 was found among differentially expressed genes in pre‐B acute lymphocytic leukemia samples with ALL1/AF4, E2A/PBX1, and BCR/ABL molecular rearrangements, and positively controls cell proliferation." (PMID 31254352, 2019).
behavioral disorders (1 paper, 2020). "Another cluster, consisting of three genes (CHD2, SCN10A, and TBC1D8), was associated with cellular assembly and organization, nervous system development and function, and ion channels, as well as neurological disease, skeletal and muscular disorders, and behavioral disorders." (PMID 33584793, 2020).
chronic lymphocytic leukemia (1 paper, 2019). "Other studies identified TBC1D8 as a target of IL4 in chronic lymphocytic leukemia and normal B cells." (PMID 31254352, 2019).
colorectal cancer (1 paper, 2022). A primary or metastatic malignant neoplasm that affects the colon or rectum. "The results of three independent CRC datasets showed significantly elevated transcription of TBC1D8 in CRC tissues and, the HPA database and our samples further validated the overexpression of TBC1D8 in colorectal cancer at the protein level." (PMID 35918393, 2022). "In this study, we identified the role of TBC1 domain family member 8 (TBC1D8) as an oncogene in colorectal cancer (CRC) by least absolute shrinkage and selection operator (LASSO) and Cox regression analysis, showing that TBC1D8 may independently predict CRC outcome." (PMID 35918393, 2022).
epilepsy (1 paper, 2020). A brain disorder characterized by episodes of abnormally increased neuronal discharge resulting in transient episodes of sensory or motor neurological dysfunction, or psychic dysfunction. "TBC1D24, a member of the same protein family as TBC1D8, regulates neuronal migration and its epilepsy-related mutation is in the Rab-GAP TBC domain, which is the same domain containing the mutation evaluated in our study." (PMID 33584793, 2020). "Alternatively, mutations in TBC1D8 have been detected in patients with intellectual disability without an epilepsy phenotype." (PMID 33584793, 2020). "Another group of genes, CHD2, SCN10A, and TBC1D8, was associated with HGF and PTEN; these two genes are related to synaptic plasticity, neuronal cell survival, and CNS development, as well as related to epilepsy." (PMID 33584793, 2020). "However, our data revealed mutations of TBC1D8 in Korean patients with LGS as well as decreased neurite outgrowth in human neuroblastoma cells by depletion of TBC1D8, suggesting that TBC1D8 is a candidate gene for LGS or epilepsy." (PMID 33584793, 2020).
hearing loss (1 paper, 2022). "A de novo heterozygous variant of TBC1D8 was identified as a candidate cause of the sporadic hearing loss in family 1575." (PMID 35248088, 2022). "The other five genes (SVEP1, CACNG1, GTPBP4, PCNX2, and TBC1D8) were categorized as Tier 4 genes, with no known association with hearing loss." (PMID 35248088, 2022).
neuroblastoma (1 paper, 2020). Neuroblastoma (NB) is the most common solid, extracranial childhood tumor. "To examine the effects of SLC25A39 and TBC1D8 on neuronal function, we depleted SLC25A39 and TBC1D8 from the SH-SY5Y neuroblastoma cell line and examined neurite outgrowth." (PMID 33584793, 2020).
cancer (4 papers, 2020 to 2024). A tumor composed of atypical neoplastic, often pleomorphic cells that invade other tissues. "Given that its Hub Gene is an indicator of SOX2, which is involved in the development and maintenance of stem-like properties in cancer cells, we considered that TBC1D8 may also be associated with tumor cell stemness." (PMID 35918393, 2022). "Previous studies have revealed the roles of TBC1D8 and TBC1D14 in other types of cancers, so these two TBC1Ds were knocked out in Hep3B cells in this study." (PMID 38766486, 2024). "The results showed that the mRNA levels of TBC1D1, TBC1D7, TBC1D8 and TBC1D14 significantly varied between different cancer stages, whereas the mRNA levels of TBC1D9b and TBC1D25 did not." (PMID 38766486, 2024). "The present study found that the expression of TBC1D8 was higher in HCC tissues than in normal liver tissues and its expression was significantly correlated with cancer stage and tumor grade." (PMID 38766486, 2024). "It should be noted that TBC1D8, another member of the TBC domain GTPase activating protein, had recently been shown to be able to drive metabolic reprogramming in cancer cells." (PMID 32226544, 2020). "To further investigate the role of TBC1Ds on the malignant feature of HCC, we knockout the expression of TBC1D8 and TBC1D14 in Hep3B cells as these two genes play vital function in other types of cancers and showed relative tighter relationship to the prognosis of patients with HCC." (PMID 38766486, 2024).
tumor (2 papers, 2022 to 2024). "The results showed that TBC1D8 and its related genes are significantly associated with many related to the tumor microenvironment, including “ANGIOGENESIS”, “DEGRADATION OF THE EXTRACELLULAR MATRIX”, “ACTIN BINDING”, and “INTEGRIN BINDING”." (PMID 35918393, 2022). "We observed that TBC1D8 knockdown significantly down -regulated the surface markers of M2 tumor-associated macrophages (TAMs) (CD206 and CD163) in THP-1 macrophages." (PMID 35918393, 2022). "Quantification of spheres showed that TBC1D8 knockdown significantly reduced both the numbers and sizes of CRC cell tumor spheres." (PMID 35918393, 2022). "To further investigate the influence of TBC1D8 expression on M2 macrophage abundance in CRC, we established a tumor–macrophage co-culture model using a transwell non-contact co-culture unit." (PMID 35918393, 2022).
colorectal (1 paper, 2022). "Taken together, these results show that the TBC1D8 gene is involved in colorectal carcinogenesis, and the underlying molecular mechanisms may include hypoxia and immune cell infiltration." (PMID 35918393, 2022).
TBC1D8 also shares sentences with these, for which no sentence is quoted: asthma (1 paper); cognitive decline (1); Intellectual disability (1); liver cancer (1); muscular disorders (1); neurological disease (1).